CDH1 (cadherin 1)
Diseases named in the same sentence as CDH1 in open-access papers (continued):
Sharing a sentence is not in itself a finding about the gene and the disease.
CDH1 also shares sentences with these, for which no sentence is quoted: liver fibrosis (30 papers); cholangiocarcinoma (23); papillary thyroid carcinoma (22); diabetic nephropathy (20); gallbladder cancer (16); myeloma (16); Infertility (14); acute kidney injury (13); gastrointestinal tumors (12); anaplastic thyroid carcinoma (11); benign prostatic hyperplasia (11); breast adenocarcinoma (11); cervical squamous cell carcinoma (11); atopic dermatitis (9); Ewing sarcoma (9); fibrosis (9); prostate (9); Sepsis (9); teratoma (9); adenoid cystic carcinoma (8); chondrosarcoma (8); chordoma (8); epithelial dysplasia (8); lung squamous cell carcinoma (8); malignant glioma (8); thyroid (8); ameloblastoma (7); Chronic colitis (7); chronic obstructive pulmonary disease (7); follicular thyroid carcinoma (7).
A further 482 diseases each share a sentence with CDH1 in 7 papers or fewer.